ATG5 (autophagy related 5)
Description:
Involved in autophagic vesicle formation. Conjugation with ATG12, through a ubiquitin-like conjugating system involving ATG7 as an E1-like activating enzyme and ATG10 as an E2-like conjugating enzyme, is essential for its function. The ATG12-ATG5 conjugate acts as an E3-like enzyme which is required for lipidation of ATG8 family proteins and their association to the vesicle membranes. Involved in mitochondrial quality control after oxidative damage, and in subsequent cellular longevity. Plays a critical role in multiple aspects of lymphocyte development and is essential for both B and T lymphocyte survival and proliferation. Required for optimal processing and presentation of antigens for MHC II. Involved in the maintenance of axon morphology and membrane structures, as well as in normal adipocyte differentiation. Promotes primary ciliogenesis through removal of OFD1 from centriolar satellites and degradation of IFT20 via the autophagic pathway. As part of the ATG8 conjugation system with ATG12 and ATG16L1, required for recruitment of LRRK2 to stressed lysosomes and induction of LRRK2 kinase activity in response to lysosomal stress (By similarity). May play an important role in the apoptotic process, possibly within the modified cytoskeleton. Its expression is a relatively late event in the apoptotic process, occurring downstream of caspase activity. Plays a crucial role in IFN-gamma-induced autophagic cell death by interacting with FADD. (Microbial infection) May act as a proviral factor. In association with ATG12, negatively regulates the innate antiviral immune response by impairing the type I IFN production pathway upon vesicular stomatitis virus (VSV) infection. Required for the translation of incoming hepatitis C virus (HCV) RNA and, thereby, for initiation of HCV replication, but not required once infection is established.
Synonyms: APG5L; ASP; APG5; hAPG5; APG5-LIKE; SCAR25
Tractability: Antibody: UniProt places it where antibodies can reach, with medium confidence. PROTAC: UniProt records ubiquitination sites on it; ubiquitination databases record sites on it; its protein half-life has been measured.
Gene: Protein-coding gene on chromosome 6 (106,045,423 to 106,326,477, reverse strand). Ensembl gene ENSG00000057663.
Subcellular location: Cytoplasm; Preautophagosomal structure membrane
Subcellular location (Human Protein Atlas): Basal body; Centrosome; Primary cilium transition zone; Vesicles
Pathways (Reactome):
Autophagy: Macroautophagy; PINK1-PRKN Mediated Mitophagy; Receptor Mediated Mitophagy
Immune System: Negative regulators of DDX58/IFIH1 signaling
Gene Ontology:
Molecular function: Atg8-family ligase activity; protein binding
Biological process: aggrephagy; autophagosome assembly; autophagy; macroautophagy; negative regulation of autophagic cell death; negative regulation of defense response to virus; positive regulation of viral translation; regulation of autophagosome maturation; cellular response to nitrogen starvation; mitophagy; piecemeal microautophagy of the nucleus; post-translational protein modification; regulation of cilium assembly; axonal transport; cellular response to nitrosative stress; chaperone-mediated autophagy; negative regulation of apoptotic process; negative regulation of innate immune response; negative regulation of programmed cell death; negative regulation of type I interferon production; positive regulation of autophagy; positive regulation of stress granule assembly; postsynaptic modulation of chemical synaptic transmission; regulation of postsynaptic membrane neurotransmitter receptor levels; response to fluoride; and 1 more
Cellular component: Atg12-Atg5-Atg16 complex; autophagosome; cytoplasm; membrane; phagophore assembly site membrane; axoneme; cytosol; phagocytic vesicle membrane; phagophore; protein-containing complex; axon; glutamatergic synapse; mitochondria-associated endoplasmic reticulum membrane contact site; postsynapse; Schaffer collateral - CA1 synapse; synapse; transferase complex
Genetic constraint (gnomAD): Loss-of-function variants: 8 observed, 19.54 expected, observed/expected ratio (o/e) 0.41, 90% interval 0.24 to 0.74. The upper end of that interval is the gene's LOEUF score, 0.74, which puts it in group 3 of 6, group 1 being the genes least tolerant of losing a copy. Missense variants: 142 observed, 238.97 expected, observed/expected ratio (o/e) 0.59, 90% interval 0.52 to 0.68. Synonymous variants: 67 observed, 75.18 expected, observed/expected ratio (o/e) 0.89, 90% interval 0.73 to 1.09.
Gene-disease validity (ClinGen):
ClinGen rates the evidence that ATG5 causes each of these diseases.
spinocerebellar ataxia, autosomal recessive 25 (autosomal recessive): Limited.
Homologues: Orthologues: chimpanzee ATG5 (100% identical), macaque ATG5 (100% identical), dog ATG5 (99% identical), pig ATG5 (98% identical), guinea pig ATG5 (97% identical), mouse Atg5 (97% identical), rat Atg5 (95% identical), zebrafish atg5 (81% identical), tropical clawed frog atg5 (73% identical), rabbit ATG5 (52% identical), Drosophila melanogaster Atg5 (47% identical), Caenorhabditis elegans atg-5 (36% identical).
Diseases named in the same sentence as ATG5 in open-access papers:
ATG5 is named in the same sentence as 365 diseases in open-access papers, as found by Europe PMC text mining. Sharing a sentence is not in itself a finding about the gene and the disease. The quoted sentences say what the papers report.
breast carcinoma (77 papers, 2010 to 2025). "It was found that either TAMs-CM or RAPA administration caused an increase in yellow and red puncta in breast cancer cells, while 3-Ma treatment or ATG5 knockdown reversed the autophagy-promoting effects of TAMs-CM." (PMID 39394189, 2024). "Atg5 level is associated with prolonged disease‐free survival in breast cancers, implying a tumor‐suppressive role." (PMID 38826147, 2024). "Expression of ATG5 in the tumor specimens is also associated with relapse-free survival in breast cancer patients." (PMID 29774126, 2018). "Moreover, ATG5 knockdown effectively prevented the increase in luminal breast cancer cell proliferation caused by ATP6AP1 overexpression." (PMID 40133274, 2025). "In addition, some studies demonstrated that elevated expression of ATG5 was associated with favorable clinical outcomes in both breast cancer and melanoma patients." (PMID 29382381, 2018). "These ATG5-dependent exosomes significantly enhance the migration and metastasis of breast cancer cells." (PMID 39893499, 2025). "Experimental knockdown of ATG5/7 or pharmacological inhibition of autophagy with chloroquine (CQ) has been shown to resensitize resistant breast cancer cells to chemotherapy." (PMID 41329030, 2025). "A significant elevation was observed in both the mRNA levels and protein expression of ATG5, an essential factor for autophagic vesicle formation, in the three breast cancer cell lines compared to MCF-10 A." (PMID 39334351, 2024). "The high expression of HSP90AA1 and ATG5 in breast cancer patients predicts poor prognosis and poor clinical outcome of tumor patients." (PMID 38263419, 2024). "Mitochondrial DNA accumulation was shown to activate the STING pathway when combining autophagy inhibition (by hydroxychloroquine treatment or knockout of Atg5 or Atg7) with irradiation in breast cancer models." (PMID 38506049, 2024). "Stable autophagy inhibition via ATG5 knockdown resulted in dormancy escape and earlier metastatic recurrence in adriamycin-induced dormant breast cancer cells compared with wild-type cells." (PMID 36831154, 2023). "On the contrary, DGAT inhibition and the suppression of autophagy through ATG5 depletion had only a minor effect on the cell death of amino acid-starved MDA-MB-231 breast cancer cells." (PMID 37835551, 2023). "Down-regulation of ZNF649-AS1 can inhibit autophagy and inhibit ATG5 expression to reverse trastuzumab resistance in breast cancer with positive HER-2." (PMID 35813295, 2022). "For example, the association between rs473543 in ATG5 and disease-free survival (DFS) of breast cancer patients undergoing chemotherapy was reported." (PMID 35992821, 2022). "For example, miR-567-enriched exosomes reversed trastuzumab resistance via suppressing autophagy by targeting ATG5(autophagy related 5), promising to serve as a potential therapeutic target for breast cancer patients." (PMID 35255950, 2022). "miR‐181a binds directly to ATG5 in luminal breast cancer, and the regulation of ATG5 by miR‐181a affects autophagy flux in MCF7." (PMID 35029026, 2022). "The effect of Atg5 on exosome production promotes the migration and metastasis of orthotropic breast cancer cells." (PMID 36457117, 2022). "Cd exposure significantly promoted the proliferation, migration, and invasion of MCF-7 and T47-D breast cancer cells by inhibiting autophagy-related 5 (ATG5)-dependent autophagic flux." (PMID 36497250, 2022). "Elevating CMA activity by downregulating autophagy-related gene 5 (ATG5)-dependent macroautophagy stimulates growth and metastasis of breast cancer cells." (PMID 33761934, 2021). "More interestingly, exosomal transmit of miR-567 from normal breast epithelial cells (MCF-10A) resensitized resistant breast cancer cells to trastuzumab by targeting autophagy-related 5 (ATG5) and thereby inhibiting autophagy." (PMID 33407894, 2021).
breast carcinoma (continued). "Conversely, positive expression of ATG5 predicts a favorable prognosis in patients with breast cancer and osteosarcoma." (PMID 34901004, 2021). "Studies in human breast cancer have shown that the expression of EPHB2 can induce the increase of ATG5/12 and LC3II, thereby inducing autophagy." (PMID 33937013, 2021). "As expected, a higher frequency of Ki67 positive, polyploid-like cells was observed in ADR-treated Atg5 knockdown mammary tumors." (PMID 33816262, 2021). "Increased CMA activity induces the tumorigenesis and metastasis of human breast cancer cells via downregulation of ATG5-mediated macroautophagy." (PMID 33375363, 2020). "The KM plotter analysis points thatsignificant upregulation of ATG3, ATG5, PIK3R4, and ATG8B to be linked with poor prognosis of Tamoxifen treated breast cancer patients." (PMID 34621117, 2020). "Downregulation of ATG5 transcription further leads to repression of macroautophagy activity, which promotes breast cancer cell metastasis." (PMID 31137558, 2019). "In fact, overexpression of ATG5 has been recently reported as a novel predictor for favorable DFS in breast cancer patients." (PMID 29382381, 2018). "For example, high expression of ATG5 suggested a superior prognosis in breast cancer, colorectal cancer, and early-stage melanoma, but indicated a poor outcome in oral squamous cell carcinoma." (PMID 30092789, 2018). "Preclinical studies have shown that inhibiting autophagy via siRNA against beclin 1 and ATG5, or pharmacological inhibitors such as 3-MA, increase the efficacy of radiotherapy in breast cancer, glioma, colorectal, and oesophageal cancer cells." (PMID 29679028, 2018). "Mechanistically, we found that elevated CMA activity mediated increased growth and metastasis of human breast cancer cells by downregulating the activity of autophagy-related gene 5 (ATG5)-dependent macroautophagy." (PMID 28684853, 2017). "In summary, the repression of ATG5 transcription by elevated CMA is implicated in the downregulation of macroautophagy activity, which further promotes breast cancer cell metastasis." (PMID 28684853, 2017). "In our study, we found that GA strongly impaired early autophagy, as shown by the decrease of LC3-II and Atg5-12 complex levels, highlighting GA as a potent early autophagy inhibitor in breast cancer SKBR3 cells." (PMID 27863425, 2016). "We found that high Bik expression in breast cancer patients was significantly correlated with increased levels of the autophagy marker, ATG5." (PMID 27120789, 2016). "Dormant breast cancer stem-like cells induced by farnesyl transferase inhibitors expressed high levels of autophagy markers, such as ATG5, ATG7, and ATG12." (PMID 26458814, 2015). "Treatment caused a dose-dependent increase in the total protein levels of LC3A/B, Beclin-1 (Atg6), Atg5, Atg7, and Atg16L1 in BT-474 breast cancer cells." (PMID 25580621, 2015). "Inhibition of autophagy by knocking down ATG5 also partially inhibited AZD2281-induced apoptosis, suggesting that autophagy contributes to AZD2281-induced cell death in BRCA mutated breast cancer cells." (PMID 25975349, 2015). "Since intracellular ROS levels are closely linked to the regulation of autophagy, we followed the autophagy biomarkers beclin-1, LC-3, Atg7 and Atg5 protein levels in breast cancer cells in which the CYP2E1 was either ectopically expressed or silenced." (PMID 24207099, 2013). "While ATG5-associated exosome production in breast cancer cells appears to be independent of ATG7, inhibitors of the V1V0-ATPase complex were shown to increase exosome production, even in ATG5-deficient (ATG5−/−) cells." (PMID 39893499, 2025).
breast carcinoma (continued). "In this section, we investigate whether BRMS1L-mediated ATG5 downregulation contributes to the inhibition of autophagy in breast cancer cells." (PMID 41282485, 2025). "In breast cancer studies, loss of ATG5 was found to significantly reduce exosome release without affecting the cellular uptake of exosomes." (PMID 39893499, 2025). "Furthermore, higher ATG3, ATG5, and ATG12 expression levels are associated with a lower overall survival rate in breast cancer patients, indicating a predictive value of these genes." (PMID 40426890, 2025). "Evidence suggested that the suppression of ATG5-mediated autophagy may contribute to the development and progression of breast cancer." (PMID 39629073, 2024). "Next, to support these findings and discard unspecific effects of the pharmacological autophagy inhibitor, CQ, we performed a knockdown of the autophagy-related protein ATG5 in two breast cancer cell lines: MCF-7 hormone receptor-positive cells and MDA-MB-231 triple-negative cells." (PMID 38228661, 2024). "Combination therapy with the autophagy inhibitor 3-MA and trastuzumab showed a better effect in HER2-positive breast cancer cells, and inhibition of the autophagy-related factors ATG5, ATG7, and Beclin1 reduced resistance to tamoxifen in ER-positive breast cancer." (PMID 36831614, 2023). "KISS1 expression inhibits ATG5/7-related autophagy to suppress breast cancer brain metastasis." (PMID 36831154, 2023). "In addition, a study utilizing RT-PCR to measure ATG5 levels in 60 breast cancer tissues found that trastuzumab-resistant patients had higher ATG5 levels than trastuzumab effective patients." (PMID 36003773, 2022). "Interestingly, similar results were obtained in the RAS mutant breast cancer cell line MDA-MB-231, pointing to an oncogenic function of ATG5/7 or the autophagic pathway in RAS-driven breast cancer cells, as it has been proposed for other cancer types." (PMID 34207792, 2021). "Moreover, decreased CMA by the modulation of LAMP2A inhibits tumor growth and metastasis by upregulating ATG5-dependent macrophages in human breast cancer." (PMID 33375363, 2020). "To test our hypothesis that it is autophagy that protects ER+ breast cancer cells from palbociclib-induced senescence at low doses, we first downregulated two crucial autophagy genes, Beclin-1 and Atg-5 (refs 29, 30)." (PMID 28653662, 2017). "Expression of Atg5 could predict favorable disease-free survival in patients with breast cancer." (PMID 29545906, 2018). "In breast cancer, hypermethylation of BECN1, LC3B, and ATG5 is frequently observed in early‐stage tumors, resulting in reduced autophagic activity, accumulation of damaged organelles, genomic instability, and tumor initiation." (PMID 41329030, 2025). "In breast cancer, lncRNA ZNF649‐AS1 induced trastuzumab resistance by increasing the expression level of ATG5 by enhancing the stability of ATG5 mRNA through binding to PTBP1." (PMID 40579921, 2025). "In early‐stage breast cancer, hypermethylation of BECN1, LC3B, and ATG5 suppresses autophagic activity, contributing to tumorigenesis." (PMID 41329030, 2025). "Collectively, these results indicated that BRMS1L suppresses ATG5 expression, which inhibits the ADM-induced protective autophagy in breast cancer cells." (PMID 41282485, 2025). "In the present study, the expression levels of autophagy-related proteins (ATG5, P62, LC3-I and LC3-II) were assessed to warrant the role of autophagy in breast cancer cells incubated with rGO." (PMID 36012549, 2022). "Autophagy markers, such as Atg5, Atg12, and LC3B, are overexpressed in dormant stem cells, such as breast cancer cells, and the suppression of autophagy by 3-MA reverses dormant expression." (PMID 33375363, 2020). "Multiple breast cancer cells, MDA-MB-231, SUM149, MDA-MB-468, and SUM159 showed increased expression of pATG1, ATG5, ATG7 and BECN1 proteins in a temporal manner in response to HNK treatment." (PMID 32963809, 2020).